CD4 (CD4 molecule)
Diseases named in the same sentence as CD4 in open-access papers (continued):
Sharing a sentence is not in itself a finding about the gene and the disease.
HIV-1 infection (continued). "Insight into the establishment and maintenance of HIV-1 infection in resting CD4+ T cell subsets is critical for the development of therapeutics targeting the HIV-1 reservoir." (PMID 33688006, 2021). "An additional IFNα-dependent mechanism for huTRIM5α-directed control of HIV-1 infection in human cell lines and primary human CD4+ T cells was recently demonstrated." (PMID 33669846, 2021). "Such an early induction of tissue CD4+ T-cell death by HIV-1 infection has also been observed in other humanized mice, such as FL-HSC-NOG, FL-HSC-NRG, and FL-HSC-DKO mice." (PMID 33924786, 2021). "In support of this explanation, CD4+ T cells from HIV-1 controllers with higher A3G expression levels were found to be more resistant to HIV-1 infection in vitro compared with CD4+ T cells from HIV-1 controllers with lower A3G expression levels." (PMID 34211449, 2021). "HIV-1 infection frequency was calculated for each participant and CD4+ T-cell subset (NV, SCM, CM, TM, EM, and TD) using the total number of sequences (intact or defective) amplified and the total number of cells collected for each subset." (PMID 34544282, 2021). "IMPORTANCE The major barrier toward the eradication of HIV-1 infection is the presence of a small reservoir of latently infected cells, which include CD4+ T cells and macrophages that escape immune-mediated clearance and the effects of antiretroviral therapy." (PMID 33472928, 2021). "Infection of human tonsillar tissue ex vivo with HIV-1 was sufficient to trigger apoptosis in CD4+ T cells during HIV-1 infection." (PMID 33481814, 2021). "Our results demonstrate a direct interaction between platelets and CD4+ T cells during HIV-1 infection." (PMID 34987521, 2021). "This was despite the fact that the relative increase in CD38+ CD4+ T cells was comparable between the vaccinia and primary HIV-1 infection cohorts, as previously reported." (PMID 33477692, 2021). "The importance of HIV-1 Env-mediated autophagy has also been identified in HIV-1 infection of CD4+ T cells as this process can selectively degrade the viral transactivator Tat, thus acting as an antiviral process." (PMID 33995324, 2021). "Resting memory CD4+ T cells were indicated to play an vital role in latent HIV-1 infection, its functions is yet warranted to be discovered in glioma." (PMID 34858984, 2021). "Our data show that HIV-1 integration into cancer-related genes occurs already during primary HIV-1 infection in activated and resting CD4+ T cells and that this preference is even more pronounced at late stages of HIV-1 infection." (PMID 33784259, 2021). "Compared to NC, SC were younger (p = 0.02), but had comparable CD4+ T cell counts, CD8+ T cell counts, and CD4+/CD8+ ratios at their pre-HIV-1 infection visit (visit 1)." (PMID 34879869, 2021). "Acute HIV-1 infection (AHI) results in the widespread depletion of CD4+ T cells in peripheral blood and gut mucosal tissue." (PMID 34753817, 2021). "Recently, CRISPR with Staphylococcus aureus Cas9 (SaCas9) delivered by a lentiviral vector improved primary CD4+ T cell resistance to HIV-1 infection." (PMID 33868262, 2021). "We next sought to further validate RORC2 as a cofactor for HIV-1 infection by mRNA depletion in primary CD4+ T cells." (PMID 34819367, 2021). "In this article we performed a meta-analysis of RNA-Seq expression profiles in samples of HIV-1 CD4+ T infected cells compared to uninfected cells to assess consistently differentially expressed genes in the context of HIV-1 infection." (PMID 33557210, 2021). "Infection of hu-PBL-SCID mice as early as 2 hours post reconstitution has led to productive HIV-1 infection and a dramatic decrease in CD4+ T cell numbers." (PMID 33868262, 2021). "The most comprehensive evidence for viral persistence has been presented for latent HIV-1 infection events residing in long-lived, resting CD4 memory T cells." (PMID 33465149, 2021).
HIV-1 infection (continued). "It is known that HIV-1 permissive cells such as microglial cells, macrophages, and CD4+ T cells exist in the CNS, and it has been suggested that ongoing inflammation triggered by HIV-1 infection in the CNS contributes to cognitive dysfunction." (PMID 33924786, 2021). "Those latter 8 HIV-1 integration sites were categorized as HIV-1 integration sites from activated CD4+ T cells in subsequent analyses since we have previously shown that productive HIV-1 infection takes place in CD4–/lo T cells." (PMID 33784259, 2021). "This study aims at performing a meta-analysis of RNA-Seq expression profiles in samples of HIV-1 infected CD4+ T cells compared to uninfected cells to assess consistently differentially expressed genes in the context of HIV-1 infection." (PMID 33557210, 2021). "Of note, preferential HIV-1 integration into cancer-related genes was already detected during primary HIV-1 infection in resting as well as in activated CD4+ T cells." (PMID 33784259, 2021). "In total, 147 HIV-1 integration sites (117 in genes) from individuals during primary HIV-1 infection were identified, with 73 (58 in genes) in activated and 74 (59 in genes) in resting CD4+ T cells." (PMID 33784259, 2021). "These mice models are capable of sustaining HIV-1 infection, replicating acute HIV-1 infection with limited CD4+ T cell lifespan." (PMID 33897659, 2021). "These long-lived macrophages are suitable for maintaining HIV-1 infection in durations comparable to those of resting memory CD4+ T cells." (PMID 33897659, 2021). "Although, it requires more time than HIV-1 infection, CD4+ T cell decline occurs more slowly in HIV-2 than in HIV-1 patients." (PMID 34832533, 2021). "To determine the ratio of intact and defective provirus present in resting CD4+ T cells, activated CD4+ T cells, and macrophages following acute HIV-1 infection, we utilized an intact provirus detection assay (IPDA)." (PMID 34962974, 2021). "Our results demonstrated that platelet-CD4+ T cell aggregates expressed higher CD38/HLA-DR and PD-1 levels than their counterparts in all groups, suggesting the potential permissiveness of platelet-CD4+ T cell aggregates to HIV-1 infection." (PMID 34987521, 2021). "Several factors affect HBV vaccine response during HIV-1 infection including CD4+ T cell counts, B cell response, vaccine formulation, schedules, and timing of antiretroviral therapy (ART)." (PMID 34960230, 2021). "In contrast, HIV-1 infection of CD4+ T cells was diminished by therapeutic treatment with all selected drugs (carbamazepine, rapamycin P < 0.05; everolimus P < 0.01)." (PMID 33637808, 2021). "His past medical history (PMH) included stable human immunodeficiency virus 1 (HIV-1) infection (undetectable viral load; CD4+ cell count 321), diabetes mellitus (DM), hypertension (HT) and ischemic heart disease." (PMID 34201947, 2021). "There has been limited analysis of the primary CD4+ T-cell transcriptional response to HIV-1 infection in vitro, and prior work has focused on gene expression changes occurring between 24 and 72 h postinfection (12, –, 14)." (PMID 34154423, 2021). "RBC viral traps expressing CD4-GpA also reduced HIV-1 infection rates of CD4+ T cells, suggesting that viral attachment to RBC viral traps effectively prevents HIV-1 virions from infecting target cells." (PMID 33723514, 2021). "In this study, we found a significant positive correlation between the levels of propionate and the peripheral blood CD4+/CD8+ ratio before HIV-1 infection in SC." (PMID 34879869, 2021). "Several studies suggest that early steps of HIV-1 infection, such as virus binding to CD4 or membrane fusion, allow the virus to modulate autophagy pathways preparing cells to be permissive for viral infection." (PMID 33995324, 2021). "In both H9 and Jurkat CD4+ T cells, HIV-1 infection resulted in depletion of USP8 proteins significantly." (PMID 34630422, 2021).
HIV-1 infection (continued). "Host genomic features of HIV-1 integration site selection remained stable during HIV-1 infection in both resting and activated CD4+ T cells." (PMID 33784259, 2021). "SC had detectable plasma HIV-1 loads, lower CD4+ T cell counts, and lower CD4+/CD8+ ratio at the post-HIV-1 infection, seroconversion visit (visit 2) compared to NC." (PMID 34879869, 2021). "HIV-1 Nef exported within the exosomes modulates exosomal miRNA composition and prompts the activation of quiescent CD4+ T lymphocytes to be permissive to HIV-1 infection and transmission." (PMID 34575480, 2021). "In HIV-1 infection, changes in cell metabolism affect the susceptibility of CD4+ T cells; HIV-infected CD4+ T cells exhibit elevated metabolic activity and metabolic potential compared with those of HIV-exposed but uninfected cells." (PMID 34603402, 2021). "In turn, these effects would result in limited HIV-1 infection and elimination of CD4+ T-cells, permitting their long-term maintenance in the BLT model." (PMID 34956215, 2021). "Previous studies have shown that the principal target cells for HIV-1 infection in vivo are memory CD4+ T cells and that transmitted HIV-1 strains are predominantly CCR5 (R5) tropic." (PMID 34154423, 2021). "HIV-1 integration sites were sequenced from longitudinally sampled resting and activated CD4+ T cells from 10 HIV-1–infected individuals followed over a period of 4–6 years after primary HIV-1 infection and 2 late presenters." (PMID 33784259, 2021). "With this in mind, we decided to address the effectiveness of ART in reversing the local (mucosal) CD4+ T lamina propria lymphocytes (LPLs) depletion and chronic immune activation observed during HIV-1 infection within the gut." (PMID 34442703, 2021). "The major barrier toward the eradication of HIV-1 infection is the presence of a small reservoir of latently infected cells, which include CD4+ T cells and macrophages that escape immune-mediated clearance and the effects of antiretroviral therapy." (PMID 33472928, 2021). "Numerous studies have repeatedly shown that HIV-1 infection downregulates cell-surface expression of CD4 and MHC-I mostly due to the expression of HIV-1 Nef." (PMID 34452453, 2021). "A typical example is SAMHD1, which acts as a host restriction factor via reducing the dNTP levels in the cytoplasm to restrict HIV-1 infection in resting CD4+ T cells." (PMID 34616406, 2021). "While CD4+ T cells and hematopoietic stem cells are the dominant models for gene editing, macrophages are also an important target for HIV-1 infection." (PMID 35126374, 2021). "The interaction between galectin-9 and TIM3 expressed on the surface of activated CD4+ T cells induce resistance of activated CD4+ T cells to HIV-1 infection and replication." (PMID 34671358, 2021). "Although CD155, as the ligand of TIGIT, CD226 and CD96, is rarely expressed on CD4 T cells, it was upregulated in acute and chronic HIV-1 infection." (PMID 33717085, 2021). "In concordance with previous reports activated emigrated LCs were more susceptible to HIV-1 infection, and thereby transmitted HIV-1 to target U87.CD4.CCR5 cells." (PMID 33637808, 2021). "HIV-1 infection reduced CD4/CD8 T cell ratios within the duodenum, colon, and blood that was not restored by full ART-mediated viral suppression in plasma." (PMID 34618690, 2021). "Here we report the development and in vivo testing of second generation CD4-based CARs (CD4CAR) against HIV-1 infection using a HSCs-based approach." (PMID 33793675, 2021). "In agreement with our previous findings, CD4+ T cells were refractory to cis HIV-1 infection at the same low, 10−3 MOI but were productively infected with a 100-fold-greater dose of 10−1 MOI." (PMID 33688006, 2021). "Treatment with carbamazepine, everolimus, or rapamycin reduced HIV-1 replication in infected ex vivo CD4+ T cells, while only therapeutic rapamycin administration intervened in ongoing HIV-1 infection in CD11c+ DCs." (PMID 33669846, 2021).
HIV-1 infection (continued). "Studies have demonstrated that activated CD4+ T cells identified by CD45RO expression are the predominantly infected cells during HIV-1 infection." (PMID 34987521, 2021). "Overall, these results indicate a clear and comparable effect of CD8+ T cells on the transcriptional programming of CD4+ T undergoing either productive or non- productive HIV-1 infection." (PMID 32941545, 2020). "The latent reservoir is established within days of HIV-1 infection and is composed mainly of long-lived memory CD4+ T cells that harbor integrated latent provirus." (PMID 33334019, 2020). "We characterized proviral transcription and chromatin development in cultures of resting primary CD4+ T-cells for four months after ex vivo HIV-1 infection." (PMID 31999790, 2020). "Env mutants with a disabled CD4bs must, however, be used because gp120 binding to cell surface CD4 interferes with HIV-1 infection and the NAb assay endpoint; a new Env protein must be produced, and NAbs to the CD4bs cannot be analyzed." (PMID 31852794, 2020). "SP can promote the degradation of the XPB subunit of TFIIH and it was shown to inhibit acute HIV-1 infection of cell lines and primary CD4+ T cells by blocking HIV-1 transcription." (PMID 33334019, 2020). "Although macrophages and DCs express all HIV-1 receptors, they are much less permissive to HIV-1 infection than CD4+ T lymphocytes." (PMID 32934085, 2020). "Previous studies have described HIV-infected patients have increased levels of IL12 receptors in CD4+ T resting lymphocytes, suggesting that IL-12 is a key modulator in HIV-1 infection." (PMID 32438744, 2020). "One of the strongest correlates for CD4+ T cell decline in HIV-1 infection is the increased frequency of CD4M T cells and a corresponding deficit of CD4N T cells." (PMID 32187205, 2020). "We have shown profound CD4+ iNKT cell subset depletion in advanced HIV-1 infection and a lesser effect of active TB in HIV-uninfected patients." (PMID 31190065, 2020). "Altogether, these data suggest important roles for CD4+ CD161+ T cells in HIV-1 infection and disease progression." (PMID 33322496, 2020). "Using an unbiased approach (RNA-seq), we here show that ex vivo HIV-1 infection of primary CD4+ T cells induces the activation of multiple solo-LTRs belonging to the ERV9 lineage of endogenous retroviruses." (PMID 33021676, 2020). "We also relate the stage of cervical disease with age, HIV-1 infection, and immune status (as measured by absolute CD4 count, CD4 percentage, and CD45 count)." (PMID 32118737, 2020). "The current profiling of glucose metabolism of CD4+ T cells in HIV-1–infected patients provide us with the basic outlines of the association between cellular metabolism and HIV-1 infection pathology." (PMID 33117366, 2020). "Newly diagnosed cases of HIV-1 infection include individuals with a late diagnosis who often have a low level of CD4 cell counts." (PMID 32076107, 2020). "Accumulating evidence demonstrates that HIV-1 infection induces an increment of aerobic glycolysis in CD4+ T cells." (PMID 33117366, 2020). "We followed HIV-1 infection of primary resting CD4 T cells and found that HIV-1 infection of IL-7–treated blood resting CD4 T cells down-regulates PSGL-1 exclusively in the HIV-1–positive cell population." (PMID 32273392, 2020). "While the role of DCs in HIV-1 infection and progression and ability to transmit infectious virus to CD4 cells by cell-cell contact has been shown, HIV interaction with DCs in the liver is less studied." (PMID 32612603, 2020). "In mice, Glut6 is upregulated by activation of T lymphocytes, while in humans, the GLUT6 protein concentration was shown to increase in CD4+ T cells on HIV-1 infection." (PMID 32013205, 2020). "That DH677.3 was better than A32 at mediating ADCC against HIV-1 clade B and C CD4 downmodulated cells makes this MAb an attractive candidate for targeting HIV-1-infected cells in vivo in the setting of HIV-1 infection." (PMID 31776278, 2020).
HIV-1 infection (continued). "In vivo compartmentalization of CD4+ T cells can be seen with tissue-resident memory cells in different contexts, including HIV-1 infection." (PMID 32970634, 2020). "Previously, we, and others, have reported associations between a higher percentage of naïve CD8+ T-cells and higher CD4+:CD8+ T-cell ratio in long-term treated HIV-1 infection, consistent with better immune recovery with ART." (PMID 32295609, 2020). "Activated primary DCs resist HIV-1 infection but can capture and transfer the virus to CD4+ T cells." (PMID 32754142, 2020). "It was reported that Glut1-mediated glucose transport is required for efficient HIV-1 infection of CD4+ T cells and thymocytes." (PMID 32516328, 2020). "Unlike hu-PBL-SCID models, this model provides an environment that is more typical of the later stages of HIV-1 infection in humans (with primary cellular and humoral immune responses present and complemented with a slower CD4+T-cell decline)." (PMID 32457941, 2020). "The relatively large sizes of CD4-VLPs likely also prevented the enhancement of HIV-1 infection of target cells in vitro, which has been observed for sCD4 at low concentrations." (PMID 32690692, 2020). "The ability of CD4-VLPs to inhibit HIV-1 infection of target cells was evaluated using pseudovirus-based TZM-bl neutralization assays." (PMID 32690692, 2020). "Optimal HIV-1 infection requires T cell activation, therefore we purified total CD4+ T cells and activated them with PHA for 3 days." (PMID 32353085, 2020). "This is consistent with our previous observation that HIV-1 infection of HeLa-CD4/CXCR4/CCR5 cells upregulates the expression of miR-500a-5p, miR-34c-3p, and miR-381-3p but not miR-93-3p." (PMID 32127461, 2020). "In this study, we characterize peripheral blood CD161+ CD4+ T cells in detail, and examine how they are affected during the earliest stages of HIV-1 infection." (PMID 33322496, 2020). "Taken together, these findings demonstrate that HIV-1 infection of primary CD4+ T cells triggers the activation of ERV9 solo-LTRs harboring transcription start sites." (PMID 33021676, 2020). "T helper cells express high levels of CD4, and, once activated by cognate antigen exposure, also express CCR5, and are therefore highly susceptible to HIV-1 infection." (PMID 32354203, 2020). "Candida specific-CD4+ T cells express more IL-2, IL-17 and CD25 and are highly susceptible to HIV-1 infection." (PMID 31910871, 2020). "Earlier studies have revealed that in HIV-1 infection, as disease progresses, the frequency of CD4+ T cells is found to decline, which in turn relates to the reduced renewal capacity and increased susceptibility of these populations of cells to apoptosis." (PMID 32971935, 2020). "HIV-1 infection and replication is characterized by directly infected CD4+ T cells while utilizing cell surface co-receptor CCR5 for specific binding process and entry." (PMID 31998567, 2020). "Additionally, the upregulation of CTLA-4 in CD4+ T-cells was reported to cause a high level of CCR5 expression on CD4+ T-cells, thereby supporting a vigorous HIV-1 infection, which suggests that CTLA-4 upregulation by HIV infection could increase CD4+ T-cell susceptibility to HIV infection." (PMID 32967229, 2020). "Concurrent levels of the exhaustion markers PD-1 and TIGIT were elevated, suggesting that the CD161+ CD4+ T cells are already exhausted during the course of HIV-1 infection as early as the viral set point, approximately one month post-infection." (PMID 33322496, 2020). "Both of the previous studies mention that IFN blocks HIV-1 infection in macrophages to a significantly larger extend than in CD4+ T-cells, pointing at a dramatic difference in the IFN response between the two cells." (PMID 33086748, 2020). "CCR6+ CD4+ T cells are highly permissive to HIV-1 infection, and are depleted from peripheral blood during chronic HIV-1 infection (CHI)." (PMID 33322496, 2020).